MMP9 (matrix metallopeptidase 9)
Diseases named in the same sentence as MMP9 in open-access papers (continued):
Sharing a sentence is not in itself a finding about the gene and the disease.
ovarian carcinoma (continued). "In the ovarian cancer tissues, further significant positive correlations were observed between DAB2 and CSC markers (CD34, ALDH1A1, CD117 (Kit)) and mesenchymal markers (MMP9, SNAI1 and MMP3) and negative correlations with mesenchymal markers (CDH2, FOXC2 and SOX10)." (PMID 37815603, 2023). "However, in ovarian cancer, MMP-2 rather than MMP-9 regulation by TGase 2 has been reported, indicating that different MMPs are regulated by TGase 2 in different types of cancer." (PMID 21943122, 2011). "Studies investigating MMP expression in ovarian cancer patients determined that MMP-9 expression correlated with the advanced stage of the disease, and clinical data suggested that elevated levels of pro-MMP-9 are of prognostic value, independent of residual disease presence." (PMID 27888810, 2016).
diabetes (306 papers, 2005 to 2026). "The capacity of MSCs to inhibit MMP-9 and enhance TJ protein expression provides a mechanistic foundation for clinical applications targeting diabetes-associated CNS disorders." (PMID 40244194, 2025). "Elevated levels of MMP‐8 and MMP‐9 are associated with more severe periodontitis and an increased risk of diabetes mellitus." (PMID 39811802, 2025). "The present study collectively demonstrates that MSC therapy ameliorates diabetes-associated neuroinflammation and neuropsychiatric complications through a mechanism involving MMP-9 inhibition and BBB restoration." (PMID 40244194, 2025). "Polymorphisms in genes encoding MMP-2 and MMP-9 have been linked to the development of microvascular complications in patients with diabetes mellitus, suggesting a genetic predisposition to altered MMP activity." (PMID 40002353, 2025). "The high levels of ROS and MMP-9 have been found to be associated with glycemic index and diabetes complications." (PMID 38422498, 2024). "Under oxidative stress, the activation of MMP-9 leads to mitochondrial abnormalities associated with diabetes, which results in retinal damage." (PMID 38999417, 2024). "Significant results of MMP-9 rs2250889 on IS susceptibility under the stratification of complications (hypertension and diabetes)." (PMID 37475739, 2023). "This supports the previous statement of increased risk of diabetes incidence in individuals with high MMP-9 levels." (PMID 37658104, 2023). "After adjusting for age, sex, smoking pack-years, alcohol consumption, hypertension and diabetes, serum levels of MMP-9 above this level were significantly associated with nephrolithiasis risk (adjusted OR = 13.43, 95% CI = 6.19–29.14)." (PMID 37332754, 2023). "The risk of diabetes incidence was found to increase in cases of high MMP-9 (β = − 5.853, p = 0.006) and high MMP-14 (β = − 31.613, p = 0.18)." (PMID 35729613, 2022). "They selected matrix metalloproteinase-9 (MMP9) as a prognostic marker for pancreatic cancer and possible adjustment to the treatment of diabetes, pancreatic cancer and associated neuropathy." (PMID 35740504, 2022). "The present report builds on other studies, which show that the minor allele of rs3918242, as a promoter region SNP of the MMP-9 gene, increases circulating levels of MMP-9 and is associated with vascular disease in type 2 diabetes mellitus." (PMID 33579197, 2021). "MMP9 deficiency mice exhibit reduced EPCs mobilization, as well as impaired wound neovascularization and healing after diabetes." (PMID 32843584, 2020). "Among patients with coronary artery disease, concurrent type 2 diabetes mellitus is associated with higher plasma levels of MMP-9." (PMID 30157791, 2018). "In chronic wounds MMP-9 is increased in wound tissue as well as wound fluids and elevated tissue levels of MMP-9 are associated with poor wound healing in diabetes." (PMID 28182694, 2017). "MMP-9 is associated with several pathological changes of diabetes mellitus including diabetic retinopathy, diabetic nephropathy and diabetic microvascular complications due to its contribution in microvascular remodeling." (PMID 26692905, 2015). "It has been previously demonstrated by a population-based study that the increase in circulating endothelial biomarkers, such as ET-1 and MMP-9, can be used to evaluate the endothelial function and predict the risk of diabetes." (PMID 26692905, 2015). "Diabetes was also associated with lower bone marrow MMP-9 expression on day 0, 1 and 7 after AMI and decreased MMP-9 activity on day 1 and 7 (p<0.05)." (PMID 23226370, 2012). "Based on our findings, we conclude that in diabetes, HHcy antagonizes PPARγ and induces production of oxygen radicals that enhances MMP-9 and inhibits TIMP-4, which in turn causes matrix remodeling, E-M uncoupling and fibrosis impairing diastolic functions." (PMID 20828387, 2010).
diabetes (continued). "Strategies that interrupt the Matrix Metalloproteinase-2 (MMP-2) and Matrix Metalloproteinase-9 (MMP-9) system have been shown to reduce the ensuing threatening risk factors of vascular complications of diabetes by alteration in Extracellular Matrix (ECM)." (PMID 21593984, 2008). "Moreover, hyperglycemia-induced oxidative stress plays a critical role in activating the expression of MMPs, particularly MMP-2 and MMP-9, which have been implicated in various vascular conditions associated with diabetes." (PMID 40276785, 2025). "Metalloproteinases, e.g., MMP-9 may be useful diagnostic biomarkers for the assessment of diabetes and related disorders." (PMID 36362386, 2022). "The risk of diabetes incidence increased with high levels of MMP-9 and MMP-14." (PMID 35729613, 2022). "Firstly, MMP-9 polymorphism may be interacted with unknown or well-known risk factors of MI, such as hypertension, diabetes, dyslipidemia, and previous coronary artery disease." (PMID 35075377, 2022). "In recent studies, MMP-9 gene modified rats which were made diabetic and their retinas were examined, rapid loss of retinal capillary cells was prevented and retinopathy in the early stages of diabetes was revealed." (PMID 35729613, 2022). "For example, excess MMP-9 activity associated with the minor allele of rs3918242 may be a therapeutic target in post-MI diabetes patients." (PMID 33579197, 2021). "The data may be important in the context of concerns about the burden of heart failure in diabetes and support the potential of MMP-9 as a diagnostic marker and/or therapeutic target post-MI in order to prevent heart failure in this setting." (PMID 33579197, 2021). "Diabetes was associated with an increase in MMP-9 and NGAL expression." (PMID 34082748, 2021). "We hypothesise that the minor allele of the MMP-9 rs3918242 SNP in patients with diabetes is associated with hypertension and/or myocardial infarction in patients without symptomatic heart failure." (PMID 33579197, 2021). "The increase in MMP-9 activity may be responsible for diabetes-associated enhanced renal production of VEGF-A." (PMID 33635529, 2021). "Decreasing the MMP-2 and MMP-9 plasma levels after intraperitoneal treatment with liposomal Curcumin can constitute valuable markers for evaluating the risk of vascular complications associated with diabetes mellitus." (PMID 30818888, 2019). "This highlights the role of MMP-9 in diabetes-associated atherothrombosis." (PMID 30157791, 2018). "The increase in MMP-9 level and activity may have important consequences for the development of vascular complications associated with diabetes." (PMID 27781209, 2016). "In conclusion, the increase in circulating levels of ET-1 and MMP-9 has been observed in subjects with MetS and might be associated with the underlying causes of the increased risk of cardiovascular diseases, diabetes mellitus and cancer in people with MetS." (PMID 26692905, 2015). "Diabetes was associated with a focal increase in MMP-9 protein in the glomeruli." (PMID 25849723, 2015). "We hypothesize that E-M uncoupling in diabetes is due in part to increased level of homocysteine causing activation of latent MMP-9, attenuation of thioredoxin and TIMP-4 in response to antagonizing PPARγ." (PMID 20828387, 2010). "The aim with the study were divided into three steps: 1) To test the association of levels of MMP-9 and a total risk load of eight cardiovascular (CV) risk factors, i.e. blood pressure, dyslipidemia, diabetes, obesity, smoking, alcohol intake, physical activity and fruit and vegetable intake." (PMID 18335048, 2008). "Given that MMP-9 is also elevated in other pathologic conditions such as inflammation, ischemia, and diabetes, our results suggest that MMP-9–mediated syndecan-1 loss could be a common pathway contributing to endothelial dysfunction across multiple retinal disease contexts." (PMID 40981101, 2025).
diabetes (continued). "In addition, a clinical study showed that the combination of VNN1 and matrix metallopeptidase 9 (MMP9) may be used as a novel blood biomarker panel to discriminate between pancreatic cancer-associated diabetes and type 2 diabetes." (PMID 37946431, 2024). "Upregulated miR-144-3p disturbed the MMP-9 pathway by inhibiting Ets1 expression in MSCs, and subsequently impaired the mobilization of EPCs from bone marrow, which provided a novel mechanism underlying diabetes-mediated re-endothelialization dysfunction post myocardial infarction." (PMID 32843584, 2020). "Experimental models of streptozotocin (STZ)-induced diabetes mellitus associate elevated levels of matrix metalloproteinases 2 (MMP-2) and 9 (MMP-9)." (PMID 40002353, 2025). "Furthermore, high MMP9 levels have been associated with endothelial cell apoptosis, increased vascular stiffness, the increased release of reactive oxygen species (ROS), and a higher risk of micro- and macro-vascular complications in patients with diabetes mellitus." (PMID 40564951, 2025). "Consistent with previous studies, MMP9 was overexpressed in patients with diabetes and streptozotocin-induced diabetic rats." (PMID 40868918, 2025). "MMP-9, as a marker of tissue damage, has been shown to increase in patients with longer diabetes duration." (PMID 38932813, 2024). "It is difficult to draw any conclusions from previous studies compared to our results since lipocalin-2 and MMP-9 levels only significantly changed when comparing patients with a diabetes duration < 5 years." (PMID 38932813, 2024). "Elevated baseline levels of MMP-9 and MMP-2 are suggested to be associated with vascular complications in diabetes." (PMID 39685536, 2024). "Higher levels of MMP-9 have been shown in patients with diabetes and increased with diabetes duration." (PMID 38932813, 2024). "The activity of vascular MMP-9 is heightened in individuals with diabetes mellitus, partly due to increased production by vascular endothelial cells." (PMID 38422498, 2024). "Diabetes increased the blood–brain barrier (BBB) permeability through upregulating matrix metalloproteinase 9 (MMP-9) expression and promoting the degradation of tight junction proteins, and hypothermia reversed this phenomenon." (PMID 37697221, 2024). "Since MMP-9 plays a major role in mitochondrial damage in diabetes, the effect of inhibition of MMP-9 on mitochondrial turnover was determined." (PMID 37596436, 2024). "Elevated expression of MMP9 has been demonstrated to contribute to the advancement of diabetes-induced OA in a rat model, and it has been recognized as a potential biomarker for OA in a study." (PMID 38509535, 2024). "The increased circulating levels of matrix metalloproteinase-9 (MMP9) is another marker of heart failure, including diabetes-induced heart failure." (PMID 38824159, 2024). "The activity of MMP-9 is heightened in individuals with diabetes, partially due to increased production by vascular endothelial cells and the influence of ROS." (PMID 38422498, 2024). "This is because the activity and expression of vascular MMP-9 in patients with diabetes mellitus are inherently elevated." (PMID 38422498, 2024). "In diabetes, for instance, acute hyperglycaemia induces human cardiac stem cell death by upregulating matrix metalloproteinase-9 (MMP9), which promotes apoptosis and pyroptosis." (PMID 39519298, 2024). "In patients with diabetes, either specific inhibition or deletion of MMP-9 has been shown to accelerate wound healing." (PMID 39803151, 2024). "In diabetic mice, MMP9 expression was significantly (p < 0.05) increased as compared with the control mice, whereas BMP-7 treatment significantly (p < 0.05) reduced diabetes-induced MMP9 gene expression." (PMID 36829889, 2023). "After multivariate analysis, we confirmed CAVI among other well-known independent predictors (CAD, diabetes, serum MMP-9) of carotid atherosclerosis." (PMID 37759829, 2023).
diabetes (continued). "MMP-9 levels are significantly elevated in plasma and retinas from patients with diabetes, and in the vitreous and retinas of DR patients." (PMID 36674425, 2023). "Specifically, in the SBECD + OTX + CHR treatment group, TIMP-1, MMP-2, MMP-3, and MMP-9 expressions dropped approximately by about 29.04, 15.12, 58.77, and 19.41 times, respectively, compared to the diabetes group." (PMID 38169923, 2023). "Metformin interferes with the pathophysiology of multiple cancers and diabetes by reducing MMP-9 expression." (PMID 36826550, 2023). "MSCs that have been exposed to hypoxia express higher levels of VEGF, IL-6, MCP1, and MMP9.These hypoxia-treated MSCs increased islet grafts in a model of streptozotocin-induced diabetes in mice with lowering of the blood glucose level." (PMID 37761001, 2023). "In pathophysiological conditions, the level of MMP-9 increases during wound healing, as well as in inflammatory processes, including arthritis, diabetes and cancer." (PMID 37893149, 2023). "Tests in animal models of diabetes have shown that the activity and expression of MMP-9 was significantly increased in vascular tissue and plasma." (PMID 37332754, 2023). "In regard to this, our results demonstrated elevated MMP-9 levels with increasing duration of diabetes." (PMID 37658104, 2023). "MMP9 concentrations did not correlate with HbA1c concentrations, but patients with diabetes had increased circulating MMP9 levels (8.8 ± 4.1 μg/mL vs. 11.4 ± 6.2 μg/mL) (P = 0.03)." (PMID 36609276, 2023). "Captopril used to treat hypertension, congestive heart failure, myocardial infarction, diabetes mellitus, and diabetic nephropathy can be used to target MMP9." (PMID 35456223, 2022). "In diabetes, there is an elevation of cardiac and plasma MMP9 levels that is accompanied by pathological remodeling." (PMID 35888760, 2022). "Wound healing is accelerated in diabetes patients with selective MMP-9 inhibition or MMP-9 deletion." (PMID 36339630, 2022). "Sirtuin 1, a multifunctional deacetylase that is inactivated in diabetes, protects mitochondria from the activation of mitochondria-damaging matrix metalloproteinase-9 (MMP-9) and the damage of mtDNA." (PMID 36016568, 2022). "When the correlation between diabetes duration and MMP-9 and MMP-14 levels was examined, it was observed that the level of these proteins increased significantly as the disease duration increased (p < 0.05)." (PMID 35729613, 2022). "Meanwhile, diabetes-induced myocardial fibrosis, as evaluated by Masson trichrome staining and Sirius Red staining and TGFβ/MMP9 transcription, were also partly attenuated in diabetic Phb2S91D/+ mice and undetectable in diabetic Phb2S91D/D mice." (PMID 39285950, 2022). "In pathophysiological conditions, MMP-9 is upregulated during development and wound healing as well as during pathologies that involve inflammatory processes, including arthritis, diabetes, and cancer." (PMID 35340213, 2022). "In diabetes, increased expression of the MMP-9 protein, as mediated by reduced methylation in the promoter, was observed in mice where diabetes was induced via streptozotocin administration." (PMID 35327470, 2022). "The serum levels of MMP3 were positively related to the male gender and hypertension, while MMP9 was positively related to the age and the male gender of patients, diabetes, and the treatment with steroids." (PMID 35075175, 2022). "High MMP-9 and MMP-14 levels are associated with rapid progression of diabetes which can be considered as prognostic factors." (PMID 35729613, 2022). "Our present study also indicated a correlation between the level of MMP-3 and MMP-9 and the duration of diabetes." (PMID 36362386, 2022). "Of note, compared to WT, diabetic kidney showed a significant increase in the expression of MMP-9 and MMP-13 at mRNA (2.18 and 0.98 fold, respectively) and protein (0.54 and 0.46 fold, respectively) levels." (PMID 36522378, 2022).